HNF1B (HNF1 homeobox B)
Diseases named in the same sentence as HNF1B in open-access papers (continued):
Sharing a sentence is not in itself a finding about the gene and the disease.
ovarian carcinoma (45 papers, 2006 to 2024). A malignant neoplasm originating from the surface ovarian epithelium. "Previous studies showed direct evidence that loss-of-function of KLF6 or HNF1B decreased expression of EXT1 in cultured mouse bone marrow-derived macrophages or ovarian cancer cell line SKOV3." (PMID 37308486, 2023). "Ultimately, the transcription factor hepatocyte nuclear factor-1-β (HNF1B), which is closely related to ovarian cancer risk 40, 41, drew our attention." (PMID 35342355, 2022). "HNF1β is associated with cancer risk in several tumors, including hepatocellular carcinoma, pancreatic carcinoma, renal cancer, ovarian cancer, endometrial cancer, and prostate cancer." (PMID 31554806, 2019). "Two independent regions within HNF1B are consistently identified in prostate and ovarian cancer genome-wide association studies (GWAS); their functional roles are unclear." (PMID 27732966, 2016). "Epigenetic inactivation of HNF1B in ovarian cancer also associates with known risk SNPs, with a similar impact on EMT." (PMID 27732966, 2016). "An epigenetic analysis has identified HNF1B as a subtype-specific susceptibility gene for ovarian cancer." (PMID 26487094, 2015). "Due to its sensitivity and specificity, HNF1β overexpression is regarded as a hallmark of OCCC among epithelial ovarian cancers." (PMID 26375553, 2015). "HNF1β inactivation has been linked to EMT in ovarian cancer." (PMID 21975049, 2011). "Too much HNF1B is associated with apoptosis and a decrease in insulin secretion whilst lack of expression is known to cause hyper proliferation and is associated with clear-cell and ovarian carcinomas." (PMID 19787084, 2008). "The association of HNF1B expression with ovarian cancer clear cell change (noted by glycogen accumulation), along with its connection to glucose homeostasis, led us to investigate a broader relation between HNF1B (and its transcriptional network) and cytoplasmic clearing." (PMID 24040285, 2013). "Still, upstream regulators of NNMT in cancer were shown to be diverse, as in BRCA1 for ovarian cancer, HNF1β for thyroid cancer, and SHH for pancreatic cancer." (PMID 36750850, 2023). "The majority of ovarian cancer clear cell carcinoma (OCCC) over-express HNF-1β; therefore, HNF1β over-expression is likely to be helpful for the diagnosis of OCCC." (PMID 36768291, 2023). "Hsu IL reported that FXYD2 was transcriptionally regulated by the transcription factor HNF1B, functioning in tumor growth via autophagy-mediated cell death and modulating the affinity of Na+/K+-ATPase in ovarian cancer." (PMID 34270462, 2021). "It was revealed by Kao and colleagues that the overexpression of HNF1B is specific for ovarian CCC amongst ovarian carcinomas." (PMID 33580750, 2021). "In a study conducted to investigate the role of GATA4 and HNF1B methylation in Ovarian cancer (OC) patients, around 32.8% HNF1B methylation positive patterns were observed in OC tissue samples compared to controls." (PMID 33580750, 2021). "Firstly, we found similar pathways relating to extra-cellular matrix re-modelling and cellular adhesion enriched in an OC model, following shRNA knock-down of HNF1B in RMG2 ovarian cancer cells (GEO, GSE37290)." (PMID 27732966, 2016). "There is an obvious overlap between regions of methylation within HNF1B in prostate and ovarian cancer tissues, with a methylation signal at the 3'-UTR in both." (PMID 27732966, 2016). "HNF1B appears to play a significant role in the etiology and early stage neoplastic development of both prostate and ovarian cancers." (PMID 27732966, 2016). "We link intronic SNPs with HNF1B expression levels and epigenetic silencing in multiple populations in both prostate and ovarian cancers, thereby suggesting a plausible mechanism of action." (PMID 27732966, 2016).
ovarian carcinoma (continued). "Conversely, the HNF1B promoter is typically unmethylated and gene expression increased in clear cell ovarian tumors and cell lines compared with other ovarian cancer subtypes." (PMID 25378557, 2015). "It was demonstrated that shRNA mediated downregulation of HNF1B sensitizes ovarian cancer cells to cisplatin- or paclitaxel-mediated cytotoxicity, through inverse regulation of HSulf1 expression." (PMID 25885815, 2015). "With respect to ovarian carcinoma, the oxidative stress related HNF-1β pathways remain largely unexplored." (PMID 23466883, 2013). "To investigate the relation between promoter methylation, HNF1B expression, and cytoplasmic clearing more broadly, we characterized HNF1B promoter methylation in freshly-frozen ovarian cancers of serous and clear cell histotype, as well as in renal CCC." (PMID 24040285, 2013). "A MEDLINE search of the literature was performed using the key words ‘endometriosis’, ‘ovarian cancer’, ‘clear cell carcinoma’, ‘estrogen receptor’, ‘Arias-Stella reaction’ and ‘HNF-1β’." (PMID 24179489, 2013). "In our study, we set out to explore the relation between HNF1B expression and cytoplasmic clearing in ovarian cancers, and more broadly in other tumor types." (PMID 24040285, 2013). "Gene-expression profiling of ovarian carcinomas identified HNF1B (hepatocyte nuclear factor 1-beta) to be amongst the most upregulated transcripts in ovarian CCC (compared to other histotypes)." (PMID 24040285, 2013). "Ovarian carcinoma cell lines where HNF1β function was knockdown by siRNA or transfection with a dominant-negative mutant showed reduced E-cadherin expression and underwent epithelial-mesenchymal-like transition, associated with Slug overexpression." (PMID 21975049, 2011). "Interestingly, silencing of HNF-1B expression secondary to promoter methylation appears to promote disease progression via epithelial-to-mesenchymal transition in both prostate and ovarian cancers." (PMID 30065837, 2018). "In addition, the oncogenic role of HNF1B has been reported in several cancers such as renal, colorectal, gastric, pancreatic, and ovarian cancer." (PMID 25885815, 2015). "HNF1β was methylated in 53 % of ovarian cancer cell lines and in 26 % of primary ovarian cancers (especially in the non-clear cell types), resulting in loss of the gene’s expression." (PMID 26464794, 2015). "HNF1B is also overexpressed in endometriosis, supporting the hypothesis that the gene may have an oncogenic role in initiating specific subtypes of ovarian cancer in patients with endometriosis." (PMID 26487094, 2015). "In ovarian cancer, downregulation of HNF1β may contribute to drug resistance, thus estoration of HNF1β function could be a therapeutic approach." (PMID 26464794, 2015). "More importantly, the positive HNF1B and Napsin A staining distinguished OCCC from other types of ovarian cancers." (PMID 38062922, 2023). "HNF1B and MYBL2 were also reported to be down regulated in renal cell carcinoma, ovarian cancer and myeloid malignancies." (PMID 31795960, 2019). "Specifically, we suggested that the transcription factor HNF1β (hepatocyte nuclear factor 1 homeobox B), a gene specifically expressed in OCCC, distinguishes this phenotype from other ovarian cancers." (PMID 26318292, 2015).
ovarian carcinoma (continued). "Recently, we have shown that HNF1β overexpression significantly influences the metabolic activity of OCCC, which is distinct from that of other ovarian cancers." (PMID 26375553, 2015). "In ovarian cancer, methylation was detected in the region covering CpGs 16-19 of HNF1B gene in over 60% tumor samples while none was found in control samples." (PMID 31636385, 2020). "High expression of FXYD2 in OCCC but not in other subtypes of epithelial ovarian cancers and normal ovarian tissues is attributed to the transcriptional upregulation of HNF1B." (PMID 26910837, 2016). "Recent and not always concordant studies analyzed the influence of HNF1B gene expression on chemosensitivity in ovarian cancer." (PMID 25885815, 2015). "HNF1β is expressed exclusively in ovarian clear cell carcinoma (OCCC) and not in other ovarian cancers, regarded as a hallmark of this tumor." (PMID 26318292, 2015). "Promoter hypermethylation, silencing HNF1B expression, has also been found in ovarian carcinomas (non-CCC), and in colorectal, gastric and pancreatic cancer cell lines." (PMID 24040285, 2013). "Comparative analysis of the difference in ovarian cancer mutation genes between the BRCA1/2 mutation group and the non-mutation group uncovered that FAM175A, EMSY, PTCH1, and HNF1B were significantly highly mutated in the group without BRCA1/2 mutations, particularly PTCH1: c.3907C>T (p.R1303C)." (PMID 38817903, 2024). "HNF1β is known as a marker of prostate and ovarian cancer but not of PDAC." (PMID 27520560, 2016). "A study has demonstrated that the expression of HNF1β is significantly upregulated in ovarian CCC cell lines, while non-CCC ovarian cancer cell lines rarely express this protein, also, reduction of HNF1β induced apoptotic cell death in ovarian CCC cell lines." (PMID 26464794, 2015). "Among epithelial ovarian cancers, the majority of CCC cases showed the expression of the HNF-1β gene, whereas non-CCC tumors hardly expressed this gene." (PMID 24179489, 2013).
clear cell carcinoma (29 papers, 2013 to 2025). "This supports the theory of endometriosis expressing HNF-1β as the precursor of endometriosis-associated clear cell carcinoma." (PMID 37189525, 2023). "Since AFP+ EC can grow in solid, papillary, and glandular patterns with variable amounts of optically clear cells and hobnail-like cells and is positive for HNF1β on IHC at least weakly, clear cell carcinoma also looms as a serious diagnostic consideration." (PMID 34977100, 2021). "HNF1B and ER (oestrogen receptor) may be used as a diagnostic panel to discriminate endometrioid from clear cell carcinoma besides serous carcinoma of the endometrium." (PMID 33580750, 2021). "The positive expression rates for HNF-1β and Napsin A were significantly higher in clear cell carcinoma than endometrioid carcinoma." (PMID 38066448, 2023). "All clear cell carcinomas of the pancreas showed strong staining of hepatocyte nuclear factor 1-beta (HNF-1β), whereas the majority of conventional ductal adenocarcinoma in the pancreas showed no or weak HNF-1β positivity." (PMID 36140448, 2022). "Incidentally, HNF1β, which is widely known as a positive marker of clear cell carcinoma of the gynecological tract, also stains positive in yolk sac tumor." (PMID 34977100, 2021). "Immunohistochemical analysis showed HNF1B nuclear staining in clear cell carcinoma specimens but minimal nuclear staining in non‐clear cell carcinoma specimens." (PMID 33580750, 2021). "Immunohistochemically, clear cell carcinomas are typically positive for HNF-1B, and often for napsin A and/or Alpha methyacyl CoA racemase (AMACR)." (PMID 33670088, 2021). "Of the 20 patients who were tested containing HNF1β, WT-1, ER, and PR, 11 (55%) had the combination of positive HNF1β, and negative WT-1, ER, and PR characteristics for the diagnosis of clear cell carcinoma." (PMID 33766002, 2021). "Stated another way, 33.3% of carcinosarcomas, 66.7% of clear cell carcinomas, 13.7% of endometrioid carcinomas, 40% of mixed type tumors, and 31.6% of serous carcinomas stained positively for HNF1β." (PMID 33986807, 2021). "In clear cell carcinoma, the patterns of detection of oestrogen receptor (ER), HNF1β and WT1 were also similar to the original tumour, despite variations in intensity." (PMID 33173111, 2020). "The extent of expression of Napsin A and HNF1B in serous carcinomas and endometrioid carcinomas is significantly lower than that in clear cell carcinomas." (PMID 30550483, 2019). "The clear cell carcinoma signature is largely dependent on the tumor microenvironment; furthermore, the expression of HNF-1β in these tumor cells was related to an epigenetic regulation of this gene through hypomethylation." (PMID 29389895, 2018). "Endogenous HNF-1β induces up-regulation of p-Chk1 expression in clear cell carcinoma TOV21G and KOC-7c cells exposed to bleomycin." (PMID 29707125, 2018). "The clear cell carcinoma signature contains genes typically expressed in this tumor type, such as Hepatocyte Nuclear Factor 1β (HNF-1β), Versican and other genes involved in oxidative stress response." (PMID 29389895, 2018). "In gynecopathology, expression of HNF-1β is commonly used in the differential diagnosis of clear cell carcinomas of the ovary and endometrium." (PMID 25884453, 2015). "Most of these studies found that expression of HNF-1β is mostly restricted to clear cell adenocarcinoma and concluded that this marker is specific for clear cell adenocarcinoma." (PMID 25884453, 2015). "On the contrary, some tumors show up-regulation of HNF-1β and expression of this protein is found in most clear cell carcinomas of pancreas, endometrium, ovary and kidney." (PMID 25884453, 2015).
clear cell carcinoma (continued). "A transcription factor, HNF-1β (hepatocyte nuclear factor-1β), is also overexpressed in clear cell carcinoma (92.3%), in atypical endometriosis (53.8%), and in benign distant endometriosis (33%)." (PMID 24804229, 2014). "HNF1β has also been reported to be useful inovarian clear cell adenocarcinoma." (PMID 39700333, 2024). "Additionally, we stained ER/PR and p16 for endometriod carcinoma, HNF1b for clear cell carcinoma, and WT1 for additive serous carcinoma, and performed a multiple rounding consensus triage." (PMID 35328131, 2022). "For example, hepatocyte nuclear factor-1beta (HNF1β) expression was initially thought to have a specificity of 93 to 100% for clear cell carcinoma; however, overtime, the specificity has been questioned as expression has been documented in a subset of serous and endometrioid carcinomas." (PMID 33986807, 2021). "Molecular signatures like these (HNF1B status or CIMP) may help classify subtypes of clear cell carcinomas." (PMID 33580750, 2021). "HNF1B (hepatocyte nuclear factor 1-beta), while considered a marker of clear cell carcinoma, may be expressed in a subset of mesonephric adenocarcinoma." (PMID 31266530, 2019). "While HNF1B and Napsin A are useful markers of clear cell carcinoma, they (especially HNF1B) may also be expressed in clear cells in endometrioid carcinomas." (PMID 30550483, 2019). "In pancreas, HNF1β is a useful marker to identify clear cell carcinomas, and its overexpression may predict worse survival." (PMID 26464794, 2015). "However, in other studies, the authors described HNF-1β expression not only in clear cell adenocarcinoma, but also in other tumor types including serous, endometrioid and mucinous carcinoma, and most types of borderline tumors." (PMID 25884453, 2015). "However, 4 cases of clear cell adenocarcinoma were used as a positive control for HNF-1β staining (all 4 cases showed strong 3+ positivity)." (PMID 25884453, 2015). "Importantly, HNF1β expression and/or loss of ARID1A expression can indicate clear cell carcinoma." (PMID 38573494, 2024). "In addition, ovarian-derived clear-cell carcinoma was positive for HNF1-β and Napsin A." (PMID 36727056, 2022). "Clear cell carcinomas frequently expressed AMACR, HNF1B, and Napsin A (83.3%, 66.7%, and 66.7%, respectively)." (PMID 33986807, 2021). "Interestingly, HNF1β, which is a marker for clear cell histology, can be positive in up to 90% of cases, whereas Napsin A may be positive in a much smaller percentage of cases, which can be valuable diagnostic marker for distinguishing GAS from clear cell carcinoma." (PMID 38366663, 2024). "HNF1β and Napsin A are typically expressed by clear cell carcinoma, but they are completely negative in this case (data not shown)." (PMID 27260518, 2016). "Thus, we conclude that HNF1β, on its own, should not be considered a specific marker for clear cell carcinoma in clinical practice." (PMID 33986807, 2021). "HNF1β showed similar lack of correlation with a specific histologic type with 71.9% of positive cases being endometrioid, 10.5% serous, 7.0% carcinosarcoma, 7.0% clear cell carcinoma, and 3.5% mixed type." (PMID 33986807, 2021). "Similarly, napsin A and HNF-1β, although helpful in identifying clear cell carcinoma, may not provide absolute specificity owing to the variability in marker expression." (PMID 40072110, 2025).
clear cell carcinoma (continued). "Advanced genomic analysis of bona-fide clear cell carcinoma cell lines also support copy number changes in typical biomarkers such at MET and HNF1B and a lack of any recurrent expressed re-arrangements." (PMID 24023729, 2013). "It has been proposed that clear cell carcinoma arises from the HNF-1β positive epithelial cells of endometriosis, whereas endometrioid carcinoma may arise from HNF-1β negative endometriosis." (PMID 24804229, 2014).